ADAMTS1 (ADAM metallopeptidase with thrombospondin type 1 motif 1)
Diseases named in the same sentence as ADAMTS1 in open-access papers (continued):
Sharing a sentence is not in itself a finding about the gene and the disease.
colorectal cancer (9 papers, 2007 to 2023). A primary or metastatic malignant neoplasm that affects the colon or rectum. "One SNP of ADAMTS1 (rs12140) decreased the risk of dying from colorectal cancer (Mullany, Herrick, Wolff, & Slattery, 2017)." (PMID 32529744, 2020). "Methylation of three of these genes, SEPT9, TMEFF2 and ADAMTS1 has been previously reported in colorectal cancer and they show partial or high level methylation in 10, 10 and 7 cancer DNAs, respectively." (PMID 24485021, 2014). "Recently, we have found another gene in the same family, ADAMTS1, to be a novel candidate for epigenetic inactivation by promoter hypermethylation in colorectal carcinomas." (PMID 17201907, 2007). "Recently, we showed that promoter hypermethylation of ADAMTS1, CRABP1, and NR3C1 was frequent among colorectal carcinomas and cell lines and to a certain extent in colorectal adenomas." (PMID 17623056, 2007).
myocardial infarction (9 papers, 2014 to 2025). Gross necrosis of the myocardium, as a result of interruption of the blood supply to the area, as in coronary thrombosis. "Polymorphisms within the ADAMTS1 gene influenced the effectiveness of a drug called statins in reducing the risk of myocardial infarction, homozygous of ADAMTS1 rs402007 had the most benefit from statins." (PMID 32529744, 2020). "A recent demonstrated that there is increased expression of ADAMTS-1 which is associated with CD68 staining in patients with acute myocardial infarction." (PMID 24732590, 2014). "Recent studies have shown that there is increased expression of ADAMTS-1 in plaques from patients with acute myocardial infarction which is associated with increased CD68 staining." (PMID 24732590, 2014). "This suggests active versican degradation (versicanolysis) mediated by ADAMTS1 during cardiac remodeling following myocardial infarction, further confirming ADAMTS1′s involvement in the pathological process of human myocardial infarction." (PMID 41440846, 2025). "Building upon this foundation, a groundbreaking study further elucidated a novel mechanotransduction pathway driven by ADAMTS1 in post-myocardial infarction cardiac fibrosis." (PMID 41440846, 2025). "Compared to patients with acute myocardial infarction and healthy volunteers, serum ADAMTS1 levels are significantly elevated in patients with acute aortic dissection (AAD), exhibiting high diagnostic sensitivity and specificity." (PMID 41440846, 2025). "The pathological significance of ADAMTS1 in human myocardial infarction has been validated through autopsy studies." (PMID 41440846, 2025). "In cardiac myofibroblasts, the proinflammatory cytokine interleukin-1α (IL-1α), a core inflammatory mediator following myocardial infarction (post-MI), paradoxically downregulates ADAMTS1 expression at both mRNA and protein levels." (PMID 41440846, 2025). "Using endothelial cell-specific ADAMTS1 overexpression and knockout models, the study confirmed that endothelial cell-derived ADAMTS1 is a key driver of cardiac dysfunction and excessive scarring following myocardial infarction." (PMID 41440846, 2025). "The discovery of this regulatory axis indicates that ADAMTS1 is a key downstream effector molecule in the “classic pathological pathway driving heart failure,” further highlighting its central role in post-myocardial infarction heart failure." (PMID 41440846, 2025). "This cell-specific paradigm is further validated in the recently identified “ADAMTS1-integrin α8” mechanotransduction axis of myocardial infarction remodeling." (PMID 41440846, 2025). "In cardiomyocytes, miR-181a seems to attenuate post-myocardial infarction tissue remodeling promoted by the MR, at least partially by suppressing A disintegrin and metalloproteinase with thrombospondin motifs 1 (ADAMTS1), a target gene of the MR." (PMID 36293446, 2022). "ADAMTS1 protein is a metalloprotease induced in the early phase of acute myocardial infarction playing an essential role in the repair of infarcted tissue and the development of heart fibrosis." (PMID 31924244, 2020). "RTX modulates ADAMTS-1 in patients that suffered from myocardial infarction." (PMID 37588971, 2023). "However, several authors suggested a HIF1-α induced upregulation of ADAMTS1 under hypoxia in endothelial cells and an early expression after myocardial infarction." (PMID 31036020, 2019). "ADAMTS1 was originally shown to be induced during the early phase of acute myocardial infarction." (PMID 29212212, 2017). "Schematic illustration showing the mechanistic pathway by which endothelial cell (EC) derived Adamts1 regulates cardiac fibroblast activation through ITGα8‐mediated mechanotransduction following myocardial infarction (MI)." (PMID 41014581, 2025).
liver fibrosis (8 papers, 2013 to 2025). "Regarding liver diseases, ADAMTS1 has been associated with the ability to activate TGF-b in liver fibrosis, as well as with NASH." (PMID 36835545, 2023). "However, ADAMTS1 promotes tumor growth and invasion, particularly in the liver; it has been linked to the exacerbation of liver fibrosis and the promotion of hepatocellular carcinoma." (PMID 40867252, 2025). "The functional role of ADAMTS1 in hepatic fibrosis was attributed to interacting with latent TGF-β to induce cleavage and activation of TGF-β in hepatic stellate cells (HSCs), because activated TGF-β is the main cytokine that triggers differentiation of HSCs to matrix-producing myofibroblasts." (PMID 38263290, 2024). "By contrast, the high expression of ADAMTS1 in cirrhotic tissues, the up-regulation of ADAMTS1 in liver fibrosis and the implication of ADAMTS1 in TGF-β activation in activated hepatic stellate cells (HCS) suggest a role of ADAMTS1 in liver fibrosis that might favor tumor onset." (PMID 33805340, 2021).
ovarian cancer (8 papers, 2007 to 2025). A primary or metastatic malignant neoplasm involving the ovary. "More recently, a comprehensive study showed that members of the ADAMTS family, including ADAMTS 1, present somatic mutations that are associated to chemotherapy outcome in ovarian cancer patients." (PMID 26916548, 2016). "This is consistent with previous studies, which showed that ADAMTS1 overexpression in ovarian cancer cells also inhibited cell migration and invasion." (PMID 40867252, 2025). "These proteases also have anti-angiogenic effects, and a review of the literature shows that the expression of ADAMTS1 is decreased in different types of cancer, including ovarian cancer, what indicates an important role this protease in ovarian health." (PMID 26916548, 2016). "Furthermore ADAMTS 1 mutations may affect the outcome of ovarian cancers." (PMID 26916548, 2016). "We conclude that progesterone acts via the progesterone receptor to modulate ADAMTS 1 and 4 levels in ovarian cancer cell lines." (PMID 26916548, 2016). "APC, CDH13, CRABP1, HOXA9, HOXB5, RASSF1A, and SCGB3A1 were found to be hypermethylated both in the primary tumours and in ovarian cancer cell lines, whereas ADAMTS1 and MGMT were hypermethylated only among cell lines." (PMID 17623056, 2007). "In another study, a higher ADAMTS-1, ADAMTS-5, aggrecan, versican and TIMP-3 expression in malignant ovarian tumors compared to benign tumors was associated with a shorter overall survival in ovarian cancer patients." (PMID 29393911, 2018). "Progesterone may exert part of its protective effects against ovarian cancer by increasing ADAMTS 1 and 4, which in turn would decrease cell migration and invasion." (PMID 26916548, 2016). "We evaluated whether sex hormones affect ADAMTS 1 and 4 expression in ovarian cancer cells." (PMID 26916548, 2016). "However, it is not clear why there was a parallel increase in TIMP-3 expression, the tissue inhibitor of ADAMTS-1 and ADAMTS-5, in malignant ovarian neoplasms compared to benign epithelial ovarian neoplasm." (PMID 29393911, 2018). "To date, there is no report implicating MALAT-1 in the regulation of MMPs or ADAMTS1 expression in ovarian cancer." (PMID 27227769, 2016). "Nonetheless, based on our current data, we hypothesize that the efficacy of MALAT-1 in promoting ovarian cancer progression could be mediated by up-regulation of MMP13 and down-regulation of MMP19 and ADAMTS1." (PMID 27227769, 2016). "Suppression of MALAT-1 resulted in downregulating the expression of MMP13 and up-regulating the expression of MMP19 and ADAMTS1 genes, indicating that MALAT-1 may involved in ovarian cancer by regulating the expression of the MMP13, MMP19, and ADAMTS1 genes." (PMID 27227769, 2016). "With regard to epigenetic mechanisms in ovarian carcinomas, ADAMTS 1 gene has been described as not methylated." (PMID 26916548, 2016). "The investigated gene promoters were chosen from loci previously reported to be methylated in ovarian cancer (n = 7; APC, CDH13, MGMT, MLH1, p14ARF, p16INK4a, RASSF1A) and from loci methylated in other tumour types (n = 6; ADAMTS1, CRABP1, HOXA9, HOXB5, NR3C1, SCGB3A1)." (PMID 17623056, 2007). "Thus, our data suggests that overexpression of MALAT-1 might promote ovarian cancer progression by regulating the expression of MMP19, ADAMTS1 and MMP13 genes." (PMID 27227769, 2016). "ADAMTS1, a metalloproteinase of the ADAM family, was found methylated in a single OV-90 cell line but not in ovarian carcinomas." (PMID 17623056, 2007).
thoracic aortic aneurysm (7 papers, 2018 to 2025). An aneurysm formed in the wall of the proximal portion of the descending aorta proceeding from the arch of the aorta. "The association between ADAMTS1 and thoracic aortic aneurysms was first suggested by early genomic profiling studies." (PMID 41440846, 2025). "For instance, ADAMTS1 deficiency induces thoracic aortic aneurysms and dissections in mice, while it is downregulated in the aorta of patients with Marfan syndrome." (PMID 35224040, 2022). "ADAMTS-1, -4 and -5 were found to be highly expressed in macrophages in human atherosclerotic plaques and in aortic tissues from patients with thoracic aortic aneurysms and dissections." (PMID 36144730, 2022). "In thoracic aortic aneurysm and dissection (TAAD), existing evidence consistently indicates that ADAMTS1 is a potent driver of disease progression." (PMID 41440846, 2025). "The role of ADAMTS1 in aortic aneurysms appears highly context-dependent, exhibiting significant differences and greater complexity in abdominal aortic aneurysms (AAA) compared to thoracic aortic aneurysms (TAAD)." (PMID 41440846, 2025).
colon carcinoma (6 papers, 2013 to 2020). "Overall, ADAMTS1 was reported to impair colon cancer progression and its expression associates with the cancer cell aggressiveness." (PMID 32456248, 2020). "ADAMTS1, belonging to the zinc-dependent metzincin superfamily, was originally identified in cachexigenic colon cancer cells." (PMID 33015704, 2020). "We didn't find significant difference in microvessel densities of colon tumors and the expression of Adamts1, 8, 12 which were reported involved in angiogenesis between Adamts18 KO mice and WT littermates." (PMID 28145888, 2017). "In this study, a possible modulation of ADAMTS-1, -4, -5 and -20 expression and distribution in colon cancer compared to healthy colon was investigated." (PMID 25786261, 2015). "Accordingly, the expression of the ADAMTS1 gene is downregulated at any colon cancer stage." (PMID 32456248, 2020). "To gain further insight into whether it is likely for the overexpressed versican to be degraded by ADAMTS as a cancer invasive mechanism, we examined ADAMTS-1, -4 and -5 expression in healthy and cancerous colon tissues and also in colon cancer cell lines of different metastatic potential." (PMID 25786261, 2015). "Similarly, a detailed analysis of genes downregulated in tumor samples resulted in the identification of protease genes including MMP28, ANPEP, ADAMTS1 and ADAMTS15, previously known to be repressed in colon carcinoma or in other tumor types." (PMID 24243807, 2013).
lymph node metastasis (6 papers, 2012 to 2025). "In GC, elevated expression levels of ADAMTS1 were significantly linked to lymph node metastasis in primary tumors." (PMID 41262238, 2025). "Enhanced expression of ADAMTS1 mRNA in lymph node metastasis or severe retroperitoneal invasion." (PMID 24213506, 2012). "The present study also investigated the association between ADAMTS1 methylation and the clinicopathological features of the patients, including age, gender, size, differentiation, depth of tumor invasion, tumor, node, metastasis (TNM) Stage and lymph node metastasis." (PMID 25936341, 2015). "Similarly, the levels of ADAMTS1 protein were also reduced in tumor tissue across different extents of lymph node metastasis and histologic grades (grade 1 to grade 3) of cancer cells, but were not lymph node metastasis or grade dependent." (PMID 35625488, 2022).
melanoma (6 papers, 2014 to 2024). A malignant, usually aggressive tumor composed of atypical, neoplastic melanocytes. "Tumour-promoting roles for ADAMTS1 have also been reported in melanoma, and ADAMTS1 deficiency can promote a pro-inflammatory landscape in melanoma." (PMID 38791926, 2024). "The extracellular protease Adamts1 (a disintegrin and metalloproteinase with thrombospondin motifs 1) has been implicated in promoting cancer, and stroma-derived Adamts1 was recently shown to drive both the growth and metastasis of melanoma." (PMID 32477466, 2020). "In addition, ADAMTS1 has been implicated in phenomena of tumor plasticity for the acquisition of endothelial-related features in sarcoma and melanoma." (PMID 24962328, 2014). "Here, we first demonstrated an in vitro EL phenotype for various melanoma cell lines that correlated with ADAMTS1 expression, and we also unveiled common gene signatures with endothelial lineages." (PMID 32230715, 2020). "While our findings with melanoma spheres confirmed the implication of recognized stemness markers, we were positively surprised that ADAMTS1 also appeared to be induced during the process and, indeed, that its inhibition blocked the formation of spheres." (PMID 32230715, 2020). "In line with the recognized plasticity of melanoma cells and the putative role of ADAMTS1 in such phenomena, we decided to evaluate stemness-related features in our tumors." (PMID 32230715, 2020). "Overall, these results encourage additional studies of the EL phenotype of our melanoma cells and the contribution of ADAMTS1." (PMID 32230715, 2020). "Using a syngeneic B16F1 melanoma model in wild type and ADAMTS1 knockout mice we found distinct stroma versus tumor functions for this protease." (PMID 27120788, 2016). "To explore how stromal Adamts1 is regulated following tumor induction, we approached the generation of human melanoma xenografts in immunodeficient mice." (PMID 27120788, 2016). "Very significantly, mouse Adamts1 expression was upregulated in both types of xenografts, independently of the endogenous levels of the protease in the human melanoma cells." (PMID 27120788, 2016). "In addition, ex-vivo assays supported a chief role for ADAMTS1 in vascular sprouting, and melanoma xenografts showed a relevant induction of its expression in stroma compartments." (PMID 27120788, 2016). "Finally, a combination of human melanoma xenografts and ex-vivo experiments confirmed the main contribution of the stroma as a supplier of ADAMTS1 and its relevance for vascular functionality." (PMID 27120788, 2016). "Indeed, melanoma sphere assays also revealed a deficient commitment to form spheres in the absence of ADAMTS1, directly correlating with stemness markers and, remarkably, also with CDH5." (PMID 32230715, 2020). "Importantly, our experiments using ADAMTS1-enriched media (secreted in the CM of melanoma cells or as exogenous recombinant protein) supported the extracellular contribution of this protease as a key factor for tumor initiation and growth, indeed corroborated by our in vivo approaches." (PMID 32230715, 2020). "Interestingly, ADAMTS1 is produced in keratinocytes and fibroblasts during wound healing, however according to our knowledge, no one indicated its elevated production in melanoma-associated keratinocytes." (PMID 36123693, 2022). "At this point, to uncover the contribution of ADAMTS1 provided by tumor cells, we inhibited the expression of endogenous Adamts1 in B16F1 melanoma cells and we further evaluated their tumorigenic properties in WT and ATS1-KO mice." (PMID 27120788, 2016). "To better understand the role of ADAMTS1 during tumor growth and to unveil its matrix-dependent actions, we generated and characterized syngeneic tumors with B16F1 murine melanoma cells in wild type (WT) and Adamts1 knockout (ATS1-KO) mice." (PMID 27120788, 2016).
melanoma (continued). "The role of ADAMTS1 has been recently described in sarcoma and melanoma models, and the analysis of IGFBP2 proteolysis in EW7 and MUM2B cells (from sarcoma and melanoma, respectively) also showed similar patterns of proteolysis." (PMID 24962328, 2014). "Importantly, we detected a significant induction of both ADAMTS1 and CDH5, implying again a role for these molecules in melanoma plasticity." (PMID 32230715, 2020).
breast tumors (5 papers, 2008 to 2022). "Nevertheless it has been recently demonstrated that ADAMTS1 promotes breast tumor cell migration by regulating the release of semaphorin 3c from the ECM." (PMID 28173833, 2017). "We also observed that the 80 kDa ADAMTS-1 band was decreased in breast tumors as compared to adjacent normal tissue samples." (PMID 23289900, 2013). "Here, we analyzed ADAMTS-1 mRNA expression in 60 human breast tumors, protein localization in 59 human samples and protein expression in 56 human samples, including normal and neoplastic tissues." (PMID 23289900, 2013). "We determined a gene expression cut-off value of 0.7 (median value) that differentiated between ADAMTS-1 low expression and high expression in breast tumors." (PMID 23289900, 2013). "Quantitative real-time RT-PCR (qPCR) was used to analyze mRNA expression level of ADAMTS-1 in 60 primary breast tumors." (PMID 23289900, 2013). "We also investigated ADAMTS-1 expression levels in breast tumor cell lines, such as MCF7 and MDA-MB-231." (PMID 23289900, 2013). "Using this cut-off, 39/60 (65%) of the breast tumors were classified as ADAMTS-1 low expressors, and 21/60 (35%) were classified as ADAMTS-1 high expressors." (PMID 23289900, 2013). "ADAMTS1 downregulation can stimulate migration and invasion in breast tumors." (PMID 35615145, 2022). "Here, we investigated mRNA and protein levels of ADAMTS-1 in normal and neoplastic tissues using qPCR, immunohistochemistry and immunoblot analyses, and we addressed the role of ADAMTS-1 in regulating migration, invasion and invadopodia formation in breast tumor cell lines." (PMID 23289900, 2013). "Similarly, we observed variable levels of ADAMTS-1 mRNA expression in a series of primary breast tumors." (PMID 23289900, 2013). "However, ADAMTS1 suppresses migration and invasion of liver and human breast tumors." (PMID 29212212, 2017).